ENSG00000293541 (novel transcript)
Gene: Long non-coding RNA gene on chromosome 6 (109,285,485 to 109,360,232, forward strand). Ensembl gene ENSG00000293541.
Gene Ontology:
Biological process: RNA processing
Cellular component: nucleolus